CBS (cystathionine beta-synthase)
Diseases named in the same sentence as CBS in open-access papers (continued):
Sharing a sentence is not in itself a finding about the gene and the disease.
breast cancer (continued). "Recently, our research group has highlighted the potential regulation of CBS and CSE in breast cancer cell lines by miR-4317 and miR-939-5p." (PMID 38250807, 2024). "Several studies have shown that human breast cancer tissues and cells lines (MDA-MB-468, MCF-7, and Hs578T) reveal the marked overexpression of CBS, CSE, and 3MST compared to normal breast cells." (PMID 38250807, 2024). "According to alcohol metabolism-involved genes, three were up-regulated (ITGA5, CBS, and SOD2), and six were down-regulated (XDH, XRCC1, MTHFR, CYP1B1, XPC, and GSTP1) among women who died for breast cancer." (PMID 39125744, 2024). "Later on, the work of Nagy and colleagues demonstrated that both CBS and CSE expression are important to support breast cancer cell proliferation and survival." (PMID 36978895, 2023). "Here, we investigated the functional role of CBS’ and 3-MST’s catalytic activity in the murine breast cancer cell line EO771." (PMID 36978895, 2023). "Four genes (AHCY, CBS, DNMT3A, and MTAP) from the methionine metabolism gene set are markers of poor prognosis for neuroblastoma and breast cancer patients." (PMID 36361596, 2022). "Among KEGG methionine metabolism genes, we have revealed five poor prognostic markers, including AHCY, CBS, DNMT3A, and MTAP, for neuroblastoma and breast cancer patients." (PMID 36361596, 2022). "Additional cancer cell types showing increased CBS expression consist majorly of cells in the NC160 collection, myeloma, and biliary tract carcinoma; breast cancers consistently showed the highest increase, as did renal tumors." (PMID 35684331, 2022). "Taken together, these data indicate that CBS and CSE are increased in breast cancer and play a significant role in breast cancer development, progression, and metastasis." (PMID 35366284, 2021). "CBS knockdown and co-culture with activated macrophages increased the levels of the 4-hydroxylnonenal (4-HNE) and malondialdehyde (MDA) breast cancer cell lines." (PMID 35366284, 2021). "Three genes were up-regulated (i.e., ITGA5, CBS, and SOD2), while six were down-regulated (i. e, XDH, XRCC1, MTHFR, CYP1B1, XPC, and GSTP1) among individuals who died of breast cancer." (PMID 32078659, 2020). "Two enzymes of this pathway, cystathionine beta synthase (CBS) and cysteine dioxygenase type 1 (CDO1), are often silenced by epigenetic inactivation in gastric and breast cancer, respectively." (PMID 28931650, 2017). "In addition, human breast cancer cells MDA-MB-468, MCF-7, and Hs578T showed significantly higher CBS levels than normal breast cells." (PMID 35684331, 2022). "CBS knockdown in the breast cancer cell lines lowered H2S and cystathionine synthesis, but not cell growth in culture." (PMID 35366284, 2021). "1,25(OH)2D3 also induced CBS expression in other murine cell lines from bone marrow, mammary carcinoma or kidney (but not in hepatocytes), suggesting that this regulation process is specific for cells and tissues that express sufficient vitamin D receptor." (PMID 32365821, 2020). "Elevated expression of CBS in tumor tissues or cell lines has been reported in colon, ovarian, prostate, and breast cancer, compared to adjacent normal tissue or nontransformed cells." (PMID 30050925, 2018). "Unlike in colon, ovarian, and breast cancer, CBS does not appear to have a functional role in melanoma." (PMID 30050925, 2018). "CBS is strongly overexpressed in breast cancer cells vs. the normal ones." (PMID 38397425, 2024). "From these findings, we conclude that endogenous H2S, generated by 3-MST and to a lower degree by CBS/CSE, significantly contributes to the maintenance of bioenergetics, proliferation and migration in murine breast cancer cells and may also exert a minor role as a cytoprotectant." (PMID 36978895, 2023).
breast cancer (continued). "In summary, endogenous H2S, primarily produced by 3-MST (and to a minor degree by CBS/CSE), significantly contributes to the maintenance of bioenergetics, proliferation and migration in the murine breast cancer cell line EO771 and may also exert a minor role as an endogenous cytoprotectant." (PMID 36978895, 2023). "However, the effect of pharmacological inhibition of endogenous H2S-producing enzymes (cystathionine-γ-lyase (CSE), cystathionine-β-synthase (CBS), and 3-mercaptopyruvate sulfurtransferase (3-MPST)) on the growth of breast cancer (BC) remains unknown." (PMID 35807290, 2022). "Interestingly, in breast cancer silencing CBS did not affect cell proliferation in culture but significantly attenuated tumor growth in a xenograft mouse model." (PMID 30050925, 2018). "To investigate CBS filamentation in situ, we employed fluorescence microscopy across various cell lines, including non-transformed (MEF, hFB), prostate cancer (PC-3), and breast cancer (BT549, MCF7, MDA-MB-231) cells." (PMID 38575566, 2024).
hepatocellular carcinoma (30 papers, 2012 to 2025). A malignant tumor that arises from hepatocytes. "Although some studies showed that CBS expression is downregulated in glioma tumor cells, gastrointestinal cancer cells, and hepatocellular carcinoma, alternatively, reduced CBS expression upregulates the 3-MST gene in glioma tumor cells." (PMID 37627515, 2023). "To validate the activity of CQ, CHX and NHX on CBS enzymatic activity, we used the human hepatoma HepG2 cell line because CBS is known to be highly expressed and active in the liver." (PMID 35743210, 2022). "On the other hand, hypoxia and radiation conditions can dramatically increase the amount of CBS in the human hepatoma cell line, HepG2." (PMID 35684331, 2022). "In hepatocellular carcinoma, inhibiting H2S generation with the CBS inhibitor CH004 supplement worsens ferroptosis." (PMID 35684331, 2022). "Inhibition of H2S production via the CBS inhibitor CH004 supplement aggravates ferroptosis in hepatocellular carcinoma." (PMID 35186934, 2022). "Reduced CBS expression was observed to be significantly correlated with higher tumor stage, higher grade, and shorter overall survival of hepatocellular carcinoma." (PMID 34970597, 2021). "In H4IIE cells (a rat hepatoma cell line), glucocorticoids were found to increase the cellular levels of CBS mRNA and protein (moreover, the presence of insulin was found to counteract this stimulatory effect)." (PMID 32365821, 2020). "For example, in hepatocellular carcinoma (HCC), downregulation of CBS is associated with disease severity and the CBS promoter is methylated in HCC, gastric, and colorectal carcinoma preventing expression." (PMID 31100816, 2019). "We also tested the effects of CH004 on the activity of endogenous CBS by incubating with HepG2 (a human liver carcinoma cell line) or HEK293T cells, which have been reported to express high levels of CBS38,39." (PMID 30258181, 2018). "Also, CBS siRNAs induced the apoptosis of SMMC-7721 cells, revealing the involvement of the CBS-induced H2S production in regulating hepatoma cell proliferation." (PMID 38250807, 2024). "Administration of 500 μM NaHS to PLC/PRF/5 hepatoma cells for 24 h significantly increases the expression of CSE, CBS and induces NF-κB activation, which in turn causes an increase in the expression of downstream pro-proliferative signaling molecules COX-2 and MMP-2." (PMID 38448410, 2024). "CBS exhibits different roles in different hepatoma cell lines." (PMID 36929586, 2023). "In contrast to the numerous studies in which CBS overexpression stimulates tumor growth in different cancer types, decreased CBS levels were also observed in glioma tumor cells, gastrointestinal cancer cells, and hepatocellular carcinoma." (PMID 34207284, 2021). "Additionally, the ferroptosis-enhancing effect of suppressing CBS has been demonstrated in hepatocellular carcinoma cells." (PMID 34281531, 2021). "Indeed, CBS was shown to be up-regulated in human hepatoma HepG2 cells upon irradiation in a dose-dependent manner." (PMID 32365821, 2020). "However, another research regarded CBS as a negative regulatory role in hepatocellular carcinoma." (PMID 35422048, 2022). "Furthermore, CBS is overexpressed in human hepatocellular carcinoma HepG2 and SMMC-7721 cells and inhibition of endogenous CBS/H2S could reduce the viability and proliferation of SMMC-7721 cells." (PMID 30805080, 2019). "Clinical evidence from patient samples strongly supports a negative regulatory role for CBS in hepatocellular carcinoma (HCC)." (PMID 30050925, 2018). "Importantly, inhibition of CBS triggers ferroptosis in hepatocellular carcinoma." (PMID 30258181, 2018). "To further examine the underlying mechanisms causing an upregulation of BHMT and a downregulation of CBS, we explored whether PPARα-activation by the agonist WY14,643 in rat hepatoma cells (Fao) can cause similar changes in gene expression in vitro as observed in the livers of obese mice." (PMID 23472083, 2013).
hepatocellular carcinoma (continued). "Another study indicates that knockdown of CBS can induce the increase in the Bax/Bcl-2 ratio, activation of caspase-3 and PARP in human hepatoma SMMC-7721 cells." (PMID 35795862, 2022). "Further analyses were needed to determine whether ERR1 plays a role in expressing CBS in cancer cells, such as the expression of CBS mRNA in hepatocellular carcinoma (HCC)." (PMID 35684331, 2022). "Clinical evidence has strongly supported the negative regulatory role of CBS in proliferative diseases, which induces autophagy and apoptosis via the PI3K/Akt/mTOR pathway in hepatocellular carcinoma (HCC) cells." (PMID 33995034, 2021). "Interestingly, many enzymes involved in SAA metabolism, including MAT1A, GNMT, BHMT, and CBS, are reported to be downregulated in human liver tumors, particularly hepatocellular carcinoma (HCC), the most common and deadly form of liver cancer." (PMID 32770044, 2020). "CBS (cystathionine beta-synthase) and CTH (cystathionine gamma-lyase) may generate cysteine via the transsulfuration pathway, but CBS or CTH inhibitors can trigger ferroptosis in hepatoma cells or NSC-34 motor neuron-like cells." (PMID 38213172, 2024). "In addition, CBS and CSE were both detected in HT1080 and hepatoma cell lines." (PMID 34257282, 2021). "The analysis of tissue samples from hepatocellular carcinoma (HCC) patients reveals a significant reduction in CBS levels compared to their surrounding non-cancerous tissues and the decrease could be correlated with poor prognosis." (PMID 33390834, 2021). "Our analysis of The Cancer Genome Atlas (TCGA) human Liver Hepatocellular Carcinoma (LIHC) dataset confirmed that key genes involved in SAA metabolism, including MAT1A, BHMT, CBS, CTH, and CDO1, are suppressed in HCC compared to normal liver." (PMID 32770044, 2020). "The negative correlation of CBS expression with the pathologic parameters in hepatocellular carcinoma (HCC) indicates its potential as a prognostic marker in HCC." (PMID 37483514, 2023).
colorectal cancer (25 papers, 2013 to 2025). A primary or metastatic malignant neoplasm that affects the colon or rectum. "Conversely, the suppression of CBS renders colorectal cancer (CRC) cells more susceptible to ferroptosis by targeting the mitochondrial tricarboxylic acid (TCA) cycle." (PMID 40948782, 2025). "CBS has been implicated in colorectal cancer carcinogenesis, its overexpression being detected even in precancerous lesions, such as hyperplastic polyps." (PMID 33223534, 2021). "Controversially to the evidence that CBS is linked to carcinogenesis, a study presents CBS as a tumor suppressor gene, claiming that in gastric and colorectal cancer the expression of CBS is inhibited by DNA methylation in association with KRAS mutations." (PMID 32714858, 2020). "Evidences showed that functional CBS gene SNP could impair CBS gene function, leading to an increase in the concentration on tHcy that further influenced aberrant DNA methylation patterns and CBS gene SNP had associations with lung cancer, colorectal cancer and head and neck squamous cell carcinoma." (PMID 24278388, 2013). "Our study delves into the intricate regulatory mechanisms of Activating transcription factor 3 (ATF3) on Cystathionine β-synthase (CBS) under cystine deprivation stress, conferring resistance to ferroptosis in colorectal cancer (CRC) cells." (PMID 38490069, 2024). "In conclusion, targeting the ATF3/CBS signaling axis along with an amino acid-restricted dietary regimen holds significant clinical potential for treating colorectal cancer." (PMID 38490069, 2024). "In summary, we have shown that in DLD1 colorectal carcinoma cells, CBS binds to the cytoskeletal proteins β-actin and β-tubulin, which has an impact on tumor growth, proliferation, and migration." (PMID 37483514, 2023). "We have found that CBS, an enzyme that endogenously produces H2S, binds to cytoskeletal β-tubulin and, to a lesser extent, also to β-actin in colorectal carcinoma-derived cells." (PMID 37483514, 2023). "Taken together, in colorectal cancer DLD1 cells, CBS binds to the cytoskeleton, modulates microtubule dynamics, and thus affects the proliferation and migration in the colorectal carcinoma stable cell line." (PMID 37483514, 2023). "CBS is inhibited in colon and colorectal cancer by promoter methylation, and CBS, mediated by methylation, can be reversed genetically or pharmacologically." (PMID 35684331, 2022). "For example, serous ovarian cancer as well as invasive urothelial bladder carcinoma, colorectal cancers and prostate cancer have shown high levels of CBS and inhibiting CBS has improved the effect of cisplatin-based chemotherapy in these neoplasms." (PMID 35084545, 2022). "CBS increased H2S synthesis in ovarian and colorectal cancers, which are critical for the bioenergetics, proliferation, and migration of cancer cells." (PMID 35684331, 2022). "Immunohistochemical analysis of CBS in 11 colorectal cancer tissues and paired normal colon epithelial tissues revealed the significantly upregulated expression of CBS in colorectal cancer tissues." (PMID 32194794, 2020). "In particular, CBS has been shown to be overexpressed in cell lines and samples of colorectal cancer and other cancer types." (PMID 30838088, 2019). "In colorectal cancer cell lines, CBS-derived H2S was suggested to support cellular proliferation, promote angiogenesis and maintain cell energy metabolism by stimulating both oxidative phosphorylation and glycolysis." (PMID 31382676, 2019). "In colorectal cancer cell lines, CBS-derived H2S was proposed to promote cell proliferation and angiogenesis and to sustain cellular bioenergetics by stimulating both oxidative phosphorylation and glycolytic ATP synthesis." (PMID 30838088, 2019). "CBS shows different effects in different colorectal cancer cell lines." (PMID 36929586, 2023).
colorectal cancer (continued). "In addition to liver cancers, colorectal cancers are also overexpressing CBS and CSE for the biosynthesis of endogenous H2S, which can regulate angiogenesis and cell proliferation." (PMID 38162986, 2023). "Therefore, we focused on the potential interaction of CBS with cytoskeletal proteins β-actin and β-tubulin and the functional relevance of the potential interaction of these proteins in colorectal carcinoma cell lines." (PMID 37483514, 2023). "This is in line with the observation of Zhang and co-workers, who demonstrated that endogenous overexpression of CBS and exogenous H2S could inhibit the proliferation and migration of colorectal carcinoma cells both in vivo and in vitro." (PMID 37483514, 2023). "In particular, CBS has been shown to be upregulated in various types of cancer, including colorectal carcinoma (CRC), squamous cell carcinoma, and ovarian, breast, and thyroid cancers." (PMID 37760083, 2023). "N1, N12‐Diacetylspermine can up‐regulate the expression of CBS and promote the proliferation of colorectal cancer cell lines SW480 and Caco2, while miR‐559 can target and inhibit CBS and inhibit the proliferation of the cells." (PMID 36929586, 2023). "To evaluate the physiological relevance of CBS in colorectal carcinoma cells, we used the CRISPR/Cas9 gene editing method to prepare the DLD1 cell line with knocked-out CBS (DLDx)." (PMID 37483514, 2023). "To study the functional role of CBS in colorectal carcinoma cells, we prepared a DLD1/CBS_del (DLDx) cell line with an inactive CBS gene through the CRISPR/Cas9 gene editing method." (PMID 37483514, 2023). "Elevated H2S levels have been detected in human colorectal cancer (CRC) biopsies, resulting from the selective upregulation of cystathionine β-synthase (CBS)." (PMID 36290680, 2022). "Similarly, IHC staining showed that CBS and ATF3 were significantly higher in colorectal cancer hepatic metastasis samples than in adjacent normal tissues." (PMID 38490069, 2024). "In the present study, working on SW480 colorectal cancer cells, we explored the effect of prolonged (24 h) exposure to NAC on H2S metabolism, particularly on its synthases (CBS, CSE and MST) and SQR, the enzyme catalyzing the limiting step of mitochondrial sulfide oxidation." (PMID 31382676, 2019). "However, experimental studies are providing increasing support for a role of the two main transsulfuration pathway enzymes CBS and CTH in colorectal cancer development through production of the gasotransmitter hydrogen sulfide." (PMID 29694444, 2018).